SGPL1 (sphingosine-1-phosphate lyase 1)
Diseases named in the same sentence as SGPL1 in open-access papers (continued):
Sharing a sentence is not in itself a finding about the gene and the disease.
breast carcinoma (5 papers, 2014 to 2026). "Since our previous metabolomics studies revealed an increased SGPL1 activity in association with successful breast cancer cell treatment in vitro, we further investigated expression and localization of SGPL1." (PMID 29718989, 2018). "The general SGPL1 downregulation and the loss of the plasma membrane expression resulted in S1P dependent stimulation of migration in the breast cancer cell lines MCF-7 and BT-20." (PMID 29718989, 2018). "Own previous studies proved that SGPL1 upregulation is leading to a successful treatment of breast cancer and osteosarcoma." (PMID 31455837, 2020). "In contrast, SGPL1 protein content was significantly lowered in all three breast cancer cell lines, verified by western blotting." (PMID 29718989, 2018). "So far, we were able to conclude that low SGPL1 content and the missing SGPL1 expression in the outer membrane leads to migratory stimulation of the breast cancer cell lines MCF-7 and BT-20." (PMID 29718989, 2018). "The general lowered SGPL1 expression was verified in immunohistochemically stained human breast cancer tissues." (PMID 29718989, 2018). "In MCF-7 breast cancer cells a much weaker expression with a more diffuse, cytosolic distribution of the SGPL1 protein was observed." (PMID 29718989, 2018). "This consideration and the fact that our previously performed metabolome studies revealed an increased SGPL1 activity in association with successful cancer cell treatment in vitro, lead to more profound SGPL1 investigations in breast cancer cells." (PMID 29718989, 2018). "By western blotting and immunofluorescence staining very low SGPL1 protein levels were found in all breast cancer samples, which correlates with other cancer studies." (PMID 29718989, 2018). "Moreover, we identified a novel SGPL1 localisation in the cytoplasm membrane of primary, epithelial breast cells in vitro, which was missing in several breast cancer cell lines." (PMID 31455837, 2020). "Decreased SGPL1 expression in breast cancer cell lines was verified by immunofluorescence staining." (PMID 29718989, 2018). "For this reason, we explored the SGPL1 expression, location and function in breast cancer cells and tissue in comparison with non-tumorigenic controls with the intent to identify the underlying regulative mechanisms." (PMID 29718989, 2018). "Expression analyses confirmed a very low SGPL1 expression in all breast cancer samples, regardless of their subtype." (PMID 29718989, 2018). "The results of previous studies suggest that the lack of SGPL1 membrane localization and overall lowered SGPL1 content permits uncontrolled extracellular S1P stimulation in the breast cancer cells which could lead to enhanced migratory activity." (PMID 29718989, 2018). "By flow cytometry SGPL1 proteins were detected on the surface of the non-tumorigenic cell lines MCF-10A and MCF-12A but not in the breast cancer cells." (PMID 29718989, 2018).
Alzheimer disease (4 papers, 2009 to 2023). A progressive, neurodegenerative disease characterized by loss of function and death of nerve cells in several areas of the brain leading to loss of cognitive function such as memory and language. "According to augmented cortical ADP concentrations reported to be essential for purinergic signaling via P2Y1R in the Alzheimer’s disease mouse model, we show here significantly increased ADP levels in the medium of SGPL1-deficient astrocytes." (PMID 37508508, 2023). "Up-regulation of SGPL1 and reduced expression of SPHK1, with a subsequent decrease in S1P, has been associated with neurodegeneration in Alzheimer’s disease and has also been described in animal models of Huntington’s disease (HD) as well as in post-mortem brain tissues from patients with HD." (PMID 36504680, 2022).
anaemia (4 papers, 2021 to 2026). "More recently, adenoviral gene transfer of human SGPL1 to newborn Sgpl1 null mice prolonged survival and averted development of anaemia, nephropathy, neurological compromise and lipid dyshomeostasis." (PMID 35904228, 2022). "Additional phenotypes reported in Sgpl1-KO pups, including anemia, high circulating cholesterol levels, and high Th-17 and other cytokines, were confirmed in our study." (PMID 33755599, 2021). "AAV-SPL treatment corrects anemia and hypercholesterolemia in Sgpl1-KO mice." (PMID 33755599, 2021). "AAV9-mediated transfer of human Sphingosine-1-phosphate lyase 1 (SGPL1) delivered to newborn Sgpl1 knockout (KO) mice, which normally die in the first few weeks of life, led to prolonged survival and ameliorated pathology, including neurodevelopmental delay, anaemia and hypercholesterolaemia." (PMID 34089057, 2021).
diabetes (4 papers, 2014 to 2022). "SGMS1, SGPL1, and SPTSSB showed increased expression only in transplanted islets with recurrent diabetes (Tx)." (PMID 36589856, 2022).
melanoma (4 papers, 2020 to 2026). A malignant, usually aggressive tumor composed of atypical, neoplastic melanocytes. "This is supported by the fact that the SGPL1 gene, encoding S1P lyase (SPL), which degrades S1P, is downregulated in melanoma cell lines relative to melanocytes, indicating its possible suppression during melanoma development." (PMID 41596686, 2026). "In accordance, the expression of SGPL1 gene, encoding for S1P lyase (SPL), is downregulated in melanoma cell lines when compared to adult or juvenile melanocytes, suggesting that SGPL1 might be downregulated during melanomagenesis." (PMID 32858889, 2020).
multiple sclerosis (4 papers, 2013 to 2023). A progressive autoimmune disorder affecting the central nervous system resulting in demyelination. "This indicates that inhibiting Sgpl1 may represent a new treatment strategy for autoimmune diseases including multiple sclerosis." (PMID 23544080, 2013). "The data suggest Sgpl1 as a novel therapeutic target for the treatment of multiple sclerosis." (PMID 23544080, 2013). "In conclusion, based on the present data, inhibitors of Sgpl1 may present a new therapeutic option for the treatment of multiple sclerosis." (PMID 23544080, 2013). "Since partial Sgpl1 deficiency appears to phenocopy the effect of FTY720 on T cell distribution, we asked if it would also confer protection in murine MOG-induced EAE, a model of multiple sclerosis that depends on the infiltration of pathogenic T cells into the brain." (PMID 23544080, 2013). "Partial Sgpl1 inhibition was shown here to confer protection in two T cell dependent in vivo models, namely in DTH as a classical inflammation model and in EAE as a disease model for multiple sclerosis." (PMID 23544080, 2013).
nephrosis (4 papers, 2017 to 2024). Pathological processes of the KIDNEY without inflammatory or neoplastic components. "AAV-SPL treatment of Sgpl1-KO mice prevents SPLIS-associated nephrosis." (PMID 33755599, 2021). "We demonstrate that SGPL1 gene replacement prevents nephrosis, developmental delay, and lipidosis in Sgpl1-KO mice and dramatically prolongs their survival." (PMID 33755599, 2021). "Similarly, Sgpl1-KO mice develop nephrosis with high urine albumin/creatinine ratio (ACR) and low serum albumin levels, accompanied by pathological changes consistent with podocyte and glomerular injury prior to their demise at the time of weaning (at 21 DOL)." (PMID 33755599, 2021). "Our cumulative results provide proof of concept for AAV-mediated SGPL1 gene transfer as a potentially curative therapy for SPLIS and provide insight into the possible pathomechanism of SPLIS nephrosis." (PMID 33755599, 2021). "These cumulative findings suggest that AAV-SPL 2.0 treatment can delay but not completely prevent the eventual onset of nephrosis and kidney pathology in Sgpl1 KO mice." (PMID 37958544, 2023).
ovarian cancer (4 papers, 2016 to 2022). A primary or metastatic malignant neoplasm involving the ovary. "The knock-down of SGPL1 induced greater cytotoxicity against the highly SGPL1-expressing ovarian cancer cell line, RMG-I, in comparison to the poorly SGPL1-expressing cell line ES-2." (PMID 31123329, 2019). "Both lead compounds exerted potent activity (GI50 value) against highly SGPL1-expressing RMG-I ovarian carcinoma cell but not poorly SGPL1expressing ES-2 cells." (PMID 31123329, 2019).
prostate carcinoma (4 papers, 2015 to 2017). A carcinoma that arises from epithelial cells of the prostate gland. "Recently, in prostate cancer, an inverse relationship between expression of SPHK1 and SGPL1 was noted and down regulation of SGPL1 increased production of S1P and was associated with resistance to docetaxel." (PMID 26493335, 2015).
rheumatoid arthritis (4 papers, 2017 to 2023). A chronic, systemic autoimmune disorder characterized by inflammation in the synovial membranes and articular surfaces. "SGPL1 inhibitors have already been tested in rheumatoid arthritis." (PMID 32290092, 2020).
autoimmune disease (3 papers, 2012 to 2022). A disorder resulting from loss of function or tissue destruction of an organ or multiple organs, arising from humoral or cellular immune responses of the individual to their own tissue constituents. "Considering the importance of IL17a producing γδT cells on the skin and other autoimmune diseases, it is crucial to elucidate the underlying molecular mechanism behind how Sgpl1 deficiency affects γδ17T cell subsets differently." (PMID 35769463, 2022). "However, partial inhibition of Sgpl1, which may lead to less pronounced and more benign increases of S1P levels, has been proposed as a therapeutic modality, in particular in autoimmune disease." (PMID 23544080, 2013).
glomerulosclerosis (3 papers, 2023 to 2026). A hardening of the kidney glomerulus caused by scarring of the blood vessels. "IL-6 is also enhanced in the serum of Sgpl1-deficient mice, which develop glomerulosclerosis and tubular atrophy." (PMID 36834691, 2023). "The renal pathology of NPHS14 closely resembles the pathology of Sgpl1−/− mice and includes not only albuminuria, podocyte effacement, and glomerulosclerosis but also tubular atrophy and tubulointerstitial fibrosis." (PMID 36834691, 2023).
Huntington disease (3 papers, 2015 to 2022). Huntington disease (HD) is a rare neurodegenerative disorder of the central nervous system characterized by unwanted choreatic movements, behavioral and psychiatric disturbances and dementia. "We verify the role of a high-ranked gene in dysregulation of sphingolipid metabolism in the disease and demonstrate that inhibiting the enzyme, sphingosine-1-phosphate lyase 1 (SPL), has neuroprotective effects in Huntington’s disease models." (PMID 28931805, 2017).
Hypercholesterolemia (3 papers, 2021). An increased concentration of cholesterol in the blood. "The results from plasma thus oppose those in global Sgpl1 knockout mice and human SPLIS patients, which may have hypercholesterolemia." (PMID 34638955, 2021).
influenza (3 papers, 2019 to 2022). An acute viral infection of the respiratory tract, occurring in isolated cases, in epidemics, or in pandemics; it is caused by serologically different strains of viruses (influenzaviruses) designated A, B, and C, has a 3-day incubation period, and usually lasts for 3 to 10 days. "Therefore, the increase in Sgpl1 gene expression observed in this study may also be related to lung injury in influenza." (PMID 34635791, 2021).
lung carcinoma (3 papers, 2012 to 2026). "In addition, SGPL1 gene mutation has been correlated with the incidence of lung cancer, providing a potential therapeutic target for lung cancer treatment." (PMID 41496093, 2026).
Nephropathy (3 papers, 2022 to 2024). A nonspecific term referring to disease or damage of the kidneys. "We find that patients diagnosed with SPLIS nephropathy in the first year of life and patients presenting with prenatal findings represent two high-risk subgroups, whereas patients harboring the R222Q SGPL1 variant fare better than the rest." (PMID 39334450, 2024). "Ongoing evaluation of auxology in all patients is required to assess any impact of SGPL1 deficiency on growth and it is possible that comorbidities including renal disease and endocrinopathy ultimately affect growth, particularly if identified late or not adequately treated." (PMID 35904228, 2022).
pulmonary fibrosis (3 papers, 2018 to 2020). Chronic progressive interstitial lung disorder characterized by the replacement of the lung tissue by connective tissue, leading to progressive dyspnea, respiratory failure, or right heart failure. "Interestingly, the partial deletion of Sgpl1 (Sgpl1+/−) in mice accentuated BLM-induced pulmonary fibrosis in mice, suggesting a balance between TGF-β-mediated SPHK1 and S1P lyase expression in regulating S1P levels and fibrogenesis." (PMID 32192225, 2020).
adenoma (2 papers, 2020 to 2023). A neoplasm arising from the epithelium. "A significant reduction in SGPL1 expression and activity was also found in adenomas and colitis-associated carcinoma in the mouse model compared to the control." (PMID 37108361, 2023). "The SGPL1 expression and activity were also significantly reduced in adenomas and colitis-associated cancer in the mouse model compared to the control model." (PMID 32630435, 2020).
alveolar rhabdomyosarcoma (2 papers, 2020 to 2022). A rapidly growing malignant mesenchymal neoplasm. "We conclude that the SGPL1 expression as well as mutation status may predict the probability for metastasis formation of pediatric rhabdomyosarcoma and other cancer entities." (PMID 31455837, 2020). "The native form of SGPL1 expression prevents S1P-induced migration and cell-colony formation of pediatric alveolar rhabdomyosarcoma (RMA) compared to SGPL1 mutant." (PMID 35565311, 2022). "In this paper we demonstrated a SGPL1 overexpression and mislocalization in pediatric alveolar rhabdomyosarcoma (RMA) cells." (PMID 31455837, 2020). "Our in vitro study presents novel evidence that SGPL1 mediated S1P degradation is an essential target for the prevention of metastasis formation in pediatric alveolar rhabdomyosarcoma." (PMID 31455837, 2020). "So far, only a few studies are available for SGPL1 expression and sphingolipid-metabolism in correlation with tumor progression and treatment success in pediatric rhabdomyosarcoma (RMS), which is the most frequent soft tissue sarcoma." (PMID 31455837, 2020). "The general SGPL1 expression signature of pediatric rhabdomyosarcoma cells was analyzed using four established RMS cell lines: RD (representing the embryonal RMS subtype), RH-30, HA-OH1 and Ax-OH-1 (representing the alveolar RMS subtype with PAX3-FOXO1 translocation)." (PMID 31455837, 2020).
fibrosis (2 papers, 2017 to 2018). the formation of excess fibrous connective tissue in an organ or tissue in a reparative or reactive process. "Moreover, a higher degree of glomerular fibrosis was observed in kidneys from Sgpl1–/– mice using Masson’s trichrome stain." (PMID 28165343, 2017).
glomerular disease (2 papers, 2020 to 2023). "We recommend patients with SGPL1-glomerulopathy to be carefully monitored for adrenal insufficiency." (PMID 32467597, 2020). "However, Sgpl1 KO mice treated in the neonatal period with AAV-SPL 2.0 showed minimal glomerular disease and almost no STAT3 pathway activation." (PMID 37958544, 2023).
preeclampsia (2 papers, 2016 to 2024). Preeclampsia is a hypertensive disorder of pregnancy that is characterized by new-onset hypertension with proteinuria presenting after 20 weeks of gestation, and depending on mild or severe forms may initially present with severe headache, visual disturbances, and hyperreflexia. "For instance, miR-125b re-directly targets sphingosine-1-phosphate lyase 1(SGPL1) that leads to enhanced IL-8 production and the development of severe preeclampsia." (PMID 39315290, 2024).
Primary hypothyroidism (2 papers, 2017 to 2023). A type of hypothyroidism that results from a defect in the thyroid gland. "We observed high levels of SGPL1 in human thyroid tissue and 4 of the patients had primary hypothyroidism; however, mild disruptions of thyroid function are a reported phenomenon with PAI, particularly in the context of untreated disease." (PMID 28165343, 2017).
psoriasis (2 papers, 2022 to 2025). An autoimmune condition characterized by red, well-delineated plaques with silvery scales that are usually on the extensor surfaces and scalp. "There should be other unexplored links between psoriasis pathology and Sgpl1 deficiency." (PMID 35769463, 2022). "SGPL1 expression decreased with the severity of psoriasis, whereas S1PR3 expression increased, showing that S1PR3 was negatively related to SGPL1 expression and was positively related to psoriasis severity in IMQ-induced mice." (PMID 39833165, 2025). "Nevertheless, evidence from tamoxifen-inducible Sgpl1 knock-out mice has shown Sgpl1 malfunctions boosted S1P but diminished C16 ceramide concentration within the skin and induced hyperkeratosis, which threatened Sgpl1 inhibition for psoriasis treatment." (PMID 35769463, 2022). "To investigate S1P levels in psoriasis, we analyzed the expression of key S1P regulatory genes (SPHK1, SPHK2, and SGPL1) using the psoriasis dataset GSE54456." (PMID 39833165, 2025).
amyloidosis (1 paper, 2026). A disorder characterized by the localized or diffuse accumulation of amyloid protein in various anatomic sites. "Although this article has made a preliminary discussion on the mechanism of SGPL1 gene mutation-related amyloidosis, further animal model verification and in-depth research on the underlying mechanisms are needed." (PMID 41496093, 2026). "We report a case of sphingosine-1-phosphate lyase 1 (SGPL1) mutation-related amyloidosis, and review the related literature." (PMID 41496093, 2026). "In our patient, amyloidosis was attributed to increased monoclonal IGA-κ protein production by plasma cells after SGPL1 mutation." (PMID 41496093, 2026). "Based on the clinical characteristics of the patient and a literature review, we speculate that this patient had multisystem amyloidosis due to the increased production of monoclonal IgA-κ protein by plasma cells as a result of a mutation in the SGPL1 gene." (PMID 41496093, 2026). "This article reports a case of amyloidosis associated with SGPL1 gene mutation." (PMID 41496093, 2026). "Therefore, we hypothesized that SGPL1 gene mutation can lead to the visceral deposition of S1P and subsequent amyloid deposits, leading to viscera-related amyloidosis." (PMID 41496093, 2026). "In this case, we focused on the role of the SGPL1 gene and its related metabolite S1P in amyloidosis, which is still unclear." (PMID 41496093, 2026). "The underlying mechanism may be that SGPL1 gene mutation increases S1P production, activates plasma cells, and results in the continuous proliferation of plasma cells and increased secretion of monoclonal IgA-κ protein, which is deposited in various organs, leading to the occurrence of amyloidosis." (PMID 41496093, 2026). "SGPL1-related amyloidosis may represent a rare “inflammation-driven” subtype of amyloidosis, characterized by predominant renal involvement and multisystem manifestations." (PMID 41496093, 2026). "SGPL1 mutation may cause multisystem amyloidosis by disrupting S1P homeostasis and increasing monoclonal IGA-κ protein production, leading to amyloidosis." (PMID 41496093, 2026). "Here, we report a case of monoclonal IgA-κ amyloidosis caused by an SGPL1 gene mutation, and review the literature on the potential effects of SGPL1 gene mutations on various organs, the underlying mechanism of SGPLI-related amyloidosis, and the prognosis of patients with this rare disorder." (PMID 41496093, 2026).